DKK1 (dickkopf Wnt signaling pathway inhibitor 1)
Diseases named in the same sentence as DKK1 in open-access papers (continued):
Sharing a sentence is not in itself a finding about the gene and the disease.
myeloma (continued). "Active vaccination against DKK1 in mouse models of MM elicited a specific T cell response against MM cells and efficiently protected mice against myeloma." (PMID 27367730, 2016). "The first evidence showing therapeutic potential of targeting DKK1 has been highlighted by the treatment of bone-related diseases including multiple myeloma, rheumatoid inflammatory disease and disorders or cancers affecting bone metabolism." (PMID 27367730, 2016). "Multiple studies have demonstrated an oncogenic role of DKK1 in diverse tumor types such as multiple myeloma, hepatoblastoma, Wilm’s tumor and hormone-resistant breast cancer." (PMID 26353782, 2015). "Higher DKK1 expression has been found in myeloma patients and has shown a positive correlation with the advanced stages of myeloma." (PMID 26659358, 2015). "DKK1 blocks Wnt3a-induced β-catenin accumulation in multiple myeloma and Wnt3a-mediated B lymphopoiesis of CD133+CD10− hematopoietic progenitor cells and CD10+ B progenitor cells." (PMID 26369691, 2015). "BHQ880inhibits DKK1 and thus promotes bone formation, which in turn inhibits myeloma-induced osteolytic disease and MMgrowth." (PMID 26659358, 2015). "An imbalance of the RANKL to OPG ratio promotes osteoclast activation while the secretion of osteoblast inhibitory molecules such as DKK-1 and activin A impairs osteogenesis, leading to myeloma induced bone disease." (PMID 25887188, 2015). "In light of anti-DKK-1-antibodies currently under clinical evaluation for patients with advanced multiple myeloma, these data warrant further research on the role of DKK-1 in solid malignancies, including prostate cancer." (PMID 25182503, 2014). "Elevated levels of DKK-1 promote bone lesions in multiple myeloma and breast cancer by inhibiting osteoblast activity." (PMID 25182503, 2014). "Elevated levels of DKK-1 were first described in the serum and bone marrow of patients with multiple myeloma." (PMID 26237142, 2013). "Recent reports showed increased expression of DKK-1 in advanced atherosclerotic plaque, and serum levels of DKK-1 gave prognostic information for patients with multiple myeloma and other malignancies, as well as osteoarthritis." (PMID 23359112, 2013). "DKK1-specific CTLs that were generated by DCs pulsed with DKK1 peptides were specifically lysed autologous primary myeloma cells and DKK1-positive cell line." (PMID 22481968, 2012). "Our finding that the DKK1 promoter is methylated and Wnt pathway is hyperactivated in advanced multiple myeloma, strongly suggests the presence of autocrine Wnt signaling in malignant plasma cells." (PMID 22363428, 2012). "The broad expression in myeloma but highly restricted expression in normal tissues, together with its functional roles as an OB formation inhibitor and a potential myeloma growth enhancer, make DKK1 an ideal and universal target for immunotherapy." (PMID 22649466, 2012). "DKK1, whose expression is down-regulated by miR-34b, was chosen because its expression is also up-regulated in many cancers including myelomas, hepatocellular carcinomas, and breast and colorectal cancers." (PMID 21949788, 2011). "Indeed, blocking the Wnt-signaling inhibitor dickkopf-1 (DKK1) with a neutralizing antibody, or stimulating Wnt signaling in myelomatous bones by using lithium chloride or Wnt3a resulted in stimulating bone formation and reducing bone loss and myeloma cell growth in vivo." (PMID 21188144, 2010). "The significant downregulation of DKK1 that resulted from PTH treatment emphasizes the critical role of this factor in myeloma-induced suppression of osteoblastogenesis." (PMID 21188144, 2010). "DKK-1 also inhibits osteoblastic differentiation and high circulating levels of DKK-1 in patients with multiple myeloma are associated with osteolytic lesions." (PMID 21029453, 2010).
myeloma (continued). "The discrepency in the condition of canonical Wnt signaling between SCs and myeloma cells in response to DKK-1 drove us to investigate the expression of DKK-1 binding receptor on the cell surface." (PMID 20846389, 2010). "Taken together, our study elucidated the mechanism by which myeloma cells and SCs in the same BM microenvironment respond differently to DKK-1 produced by MM cells." (PMID 20846389, 2010). "Compared with myeloma cells, the SCs from MM patients overexpress DKK-1 binding receptors LRP5/6 and Krm1/2 in response to DKK-1 secreted by myeloma cells, which results in intracellular Wnt signaling inhibition." (PMID 20846389, 2010). "Additional studies will be needed in order to understand the impact of DKK1 on the Wnt-induced proliferation of myeloma cells." (PMID 20465808, 2010). "Osteoblast progenitors and myeloma cells from a myeloma patient share the same bone marrow (BM) microenvironment, but respond differently to DKK-1 secreted by myeloma cells." (PMID 20846389, 2010). "In the present study, we demonstrated that most of the HMCLs and the primary myeloma cells produced DKK-1 protein, consistent with the previous reports." (PMID 20846389, 2010). "The binding capability of DKK-1 binding receptors to DKK-1 on primary myeloma cells and SCs was detected by flow cytometry assay." (PMID 20846389, 2010). "Although previous results support the high specificity and the great potentiality of serum DKK-1 as a biomarker for detection of myeloma/lung and esophageal carcinomas at an early stage and for monitoring of the relapse of the disease." (PMID 21029453, 2010). "DKK-1 is secreted by myeloma cells and is over-expressed in patients with advanced myeloma bone disease, as shown by measurement of DKK-1 levels in both bone microenvironment and serum." (PMID 19747396, 2009). "It should also be mentioned that during the last years there has also been increasing interest in the role of Dickkopf 1 (DKK-1) in multiple myeloma." (PMID 19747396, 2009). "In multiple myeloma, Dkk-1 is readily detectable in the blood of individuals in the later stages of the disease who have characteristic osteolytic bone lesions." (PMID 17987039, 2007). "It is possible, however, that the host tissue interacts with the tumour, resulting in upregulation of the expression of Dkk-1, a phenomenon observed in the case of multiple myeloma." (PMID 17987039, 2007). "DKK1, for example, has been recently reported by our group to play an important role in the development of osteolytic lesions in multiple myeloma, but its possible role in USPC pathogenesis and/or progression has not been elucidated." (PMID 15785748, 2005). "This pro-proliferative sign is not specific to pDCs, as mesenchymal stem cells (MSCs) are another cell type that support multiple myeloma proliferation directly via the suppression of T cells through the PD-1 axis, and others such as the DKK1+ MM cells and Il-6-producing undifferentiated MSCs." (PMID 41374932, 2025). "In addition, IL-6 enhances bone resorption by promoting the proliferation of Dickkopf-1 (DKK-1)-secreting myeloma cells, but DKK-1 secretion is blocked after IL-6 neutralizing agents." (PMID 35328533, 2022). "A study supported that hypoxia stimulates DKK1 production in myeloma cells." (PMID 35681577, 2022). "Silencing CREB reduced the inhibition of osteoblast formations by myeloma-produced DKK1." (PMID 35681577, 2022). "Especially in myeloma cells, DKK1 was secreted to inhibit function of osteocytes." (PMID 36213576, 2022). "Since an anti-DKK-1 neutralizing antibody has already been developed and investigated for the treatment of myeloma, future studies could evaluate the effect of this antibody in patients with HCC." (PMID 35269944, 2022).
myeloma (continued). "For this reason, myeloma cells inhibit osteoblasts through the release of distinct secretory factors such as dickkopf-related protein 1 (DKK1), secreted frizzled-related protein 2 (sFRP2) and transforming growth factor beta (TGFβ) to overcome the tumor-suppressive effects of osteoblasts." (PMID 35847862, 2022). "DKK1 has a clear and vital role in the pathogenesis of myeloma bone disease." (PMID 33420361, 2021). "Herein, we provide evidence that hypoxia promotes DKK1 expression in myeloma cells." (PMID 33420361, 2021). "Taken together, these results suggest that the inhibition of sclerostin and/or inhibitors of DKK1 may be promising tools to promote osteoblast activity, leading to increased subsequent bone deposition in multiple myeloma bone disease." (PMID 33572757, 2021). "This suggests a possible correlation between these abnormally expressed genes and myeloma-related bone disease, but how they regulate DKK1 expression is unknown." (PMID 33420361, 2021). "Active DKK-1 vaccination has been characterized in vitro and in vivo, and the improvement through the addition of antigens or peptide sequences has been evaluated for multiple myeloma, thereby increasing the potential therapeutic value of DKK-1 for this tumor." (PMID 34451907, 2021). "As an example, a DKK-1 expression increase could be an early phenomenon during multiple myeloma relapse, indicating that levels of this protein and their clinical significance can vary according to tumor progression (when)." (PMID 34451907, 2021). "DKK1 has been utilized as a potential target for immunotherapy in patients with myeloma." (PMID 34143198, 2021). "A neutralizing DKK1 antibody reduced primary myeloma burden and increased bone formation." (PMID 34093545, 2021). "DKK1 and sFRP-2 are expressed in multiple myeloma cells of patients with bone lesions." (PMID 33634031, 2020). "It was not a new idea that DKK proteins may be promising targets for therapy against cancer disease, as anti-DKK1 had been reported beneficial for multiple myeloma." (PMID 31830954, 2019). "In addition, there as a statistically significant increase in calcium deposition upon treatment with DKK1 antibody in co-cultures of pre-osteoblasts plus multiple myeloma cells." (PMID 29867053, 2018). "The expression of DKK1 in NS-1 mouse myeloma cells was analyzed by western blot." (PMID 29416605, 2018). "Inhibition of IL-6 from MSC-conditioned media slowed the proliferation of DKK-1 secreting myeloma cells treated with this media, suggesting that in the myeloma environment, IL-6 increases bone resorption through promoting proliferation of DKK-1-secreting myeloma cells." (PMID 30671025, 2018). "Taken together these results suggest that inhibitors to DKK1 may be promising targeted therapeutics that promote osteoblast differentiation and subsequent bone deposition in patients with established multiple myeloma bone disease." (PMID 29867053, 2018). "Dickkopf-1 (DKK1) is an ideal target for the immunotherapy of multiple myeloma." (PMID 29416605, 2018). "In our study, we determinated that DKK1 protein was expressed in NS-1 mouse multiple myeloma." (PMID 29416605, 2018). "Hence, regulating DKK1 function or expression was suggested as an important therapeutic target in tumor-induced bone resorption and multiple myeloma." (PMID 28178355, 2017). "Interestingly, short-term treatment (5 h) with PTC-209 was found to induce DKK1 expression in myeloma cells as well (up to 5.0 ± 1.9-fold increase, P < 0.05) (data not shown)." (PMID 26935956, 2016). "However, results should be interpreted with caution because some patients treated with anti-DKK1 antibodies were also receiving anti-myeloma therapy." (PMID 27367730, 2016). "Wnt3a-induced OPG expression could be diminished in osteoblasts co-cultured with a DKK1-expressing multiple myeloma (MM) cell line or primary MM cells." (PMID 26369691, 2015). "The clinical efficacy of DKK-1 inhibition is currently tested in patients with multiple myeloma." (PMID 25182503, 2014).
myeloma (continued). "In light of current clinical trials evaluating the efficacy of anti-DKK-1 antibody therapies in multiple myeloma and solid malignancies, the measurement of DKK-1 in prostate cancer may gain clinical relevance." (PMID 25182503, 2014). "Bortezomib can also decrease RANKL and DKK1 levels in the serum of myeloma patients." (PMID 25788856, 2014). "In murine models of myeloma, inhibition of DKK-1 reduced the extent of osteolytic lesions." (PMID 24528599, 2014). "Similarly, a neutralizing antibody against Wnt inhibitor Dkk1 (Dickkopf1), which is in Phase I/II clinical trials for multiple myeloma, has been observed to have anabolic bone activity." (PMID 24804256, 2014). "A decreased tumour burden, following DKK-1 inhibition has also been observed in multiple myeloma." (PMID 25182503, 2014). "Dickkopf 1 (DKK1) and IL-3 may contribute to the inhibitory effects of multiple myeloma cells on osteoblast differentiation." (PMID 22792345, 2012). "DKK1 inhibits the canonical Wnt pathway, which mediates the differentiation of osteoblast progenitor cells, DKK1 expression of multiple myeloma cells could inhibit osteoblastogenesis." (PMID 22792345, 2012). "DKK1 (peptide)-specific CTLs can effectively lyse primary myeloma cells in vitro." (PMID 22649466, 2012). "Similar to DKK1, secretion of the Wnt inhibitor sFRP2 by MM cells may also promote myeloma bone disease." (PMID 22363428, 2012). "Likewise, the highly expressed DKK-1 binding receptors on the SCs from MM patients in our study probably result from the DKK-1 secretion by myeloma cells in the same BM milieu." (PMID 20846389, 2010). "It has been shown that primary myeloma cells from osteolytic MM patients significantly overexpressed the Wnt inhibitor DKK-1 in comparison with the plasma cells from patients with monoclonal gammopathy of undetermined significance (MGUS) and normal plasma cells." (PMID 20846389, 2010). "Flow cytometry results showed that recombinant His-DKK-1 fusion protein could specifically bind the DKK-1 binding receptors on the myeloma cells and SCs." (PMID 20846389, 2010). "Similarly, any therapy that decreases δ (e.g., Dkk-1), should reduce the myeloma burden, slow the progression of the disease, and improve bone mass." (PMID 19724279, 2009). "Additionally, DKK1 orchestrates the accrual and function of MDSCs in malignancies, is ubiquitously acknowledged as a potent tumor-affiliated antigen in multiple myeloma, and has been anointed as an innovative immunotherapy target for myeloma." (PMID 37796226, 2023). "In myeloma, DKK1 could be at the origin of ASC senescence that we observed." (PMID 31083455, 2019). "Increasing Wnt signalling in the bone microenvironment in multiple myeloma with anti-DKK1 antibody or inhibition of glycogen synthase kinase-3β (GSK-3β) with lithium chloride resulted in the inhibition of myeloma bone disease as shown in a murine model of myeloma." (PMID 29535427, 2018). "Indeed, the BHQ880 anti-DKK1 antibody has been tested in patients with multiple myeloma." (PMID 27367730, 2016). "Finally, overexpression of DKK1 in glucocorticoid-induced osteoporosis as well as in osteosarcoma and osteolytic metastatic bone disease in multiple myeloma led to the hypothesis that DKK1 is a strong candidate gene for the regulation of bone homeostasis." (PMID 24138842, 2013). "In multiple myeloma (MM), aberrant auto-and/or paracrine activation of canonical Wnt signaling promotes proliferation and dissemination, while overexpression of the Wnt inhibitor Dickkopf1 (DKK1) by MM cells contributes to osteolytic bone disease by inhibiting osteoblast differentiation." (PMID 22363428, 2012). "Because DKK1 is expressed by Hg myeloma cells and PTH treatment resulted in reduced growth of these cells in myelomatous bones, DKK1 downregulation could be a result of direct effects of PTH on osteoblasts, it could be an epiphenomenon of reduced tumor burden, or it could be a combination of both." (PMID 21188144, 2010).
myeloma (continued). "Another potential therapeutic target for myeloma bone disease in the canonical Wnt/ß-catenin pathway is Dickkopf-related protein 1 (DKK-1), an inhibitor of the pathway secreted by myeloma cells in addition to osteoblasts and bone marrow stromal cells (BMSC)." (PMID 40862742, 2025). "Another study reported that DKK-1 binds CKAP4 to activate NF-kB signaling and drug resistance in multiple myeloma." (PMID 38067123, 2023). "In their study, DKK1 was found to be responsive to the JNK signaling cascade, and they assumed that the sensitivity of myeloma cells in the early stages to various stresses activated JNK signaling, thereby increasing DKK1 expression." (PMID 35355709, 2022). "There is currently an ongoing pilot phase 1 study exploring the application of the DKK1 vaccine in patients with MGUS and stable or smoldering myeloma (NCT03591614)." (PMID 36077618, 2022). "In a phase IB multicenter dose determination clinical study, a humanized monoclonal antibody targeting DKK1, BHQ880 in combination with ZA and anti-myeloma treatment increased bone strength and density." (PMID 36230523, 2022). "Furthermore, as part of a phase I/II clinical trial, an inhibitor of DKK1, which is also involved in the Wnt signaling pathway, was found to increase osteoblast differentiation and calcium deposition in co-cultures of osteoblasts plus multiple myeloma cells in-vitro." (PMID 33572757, 2021). "KG501, a CREB inhibitor, reversed DKK1 expression in myeloma cells exposed to hypoxia, and CREB overexpression upregulated DKK1 in myeloma cells." (PMID 33420361, 2021). "Another DKK1 antibody BHQ880, developed by Novartis Pharmaceuticals, had completed phase 1B trials in multiple myeloma." (PMID 34093545, 2021). "In a mouse myeloma model with bone lesions generated by transplanting a human myeloma cell line into NOD-SCID mice, elevated blood levels of human DKK1 were observed, and while human sclerostin level was undetected, mouse sclerostin level was elevated." (PMID 31698687, 2019). "LDN and BMPR1a-FC could inhibit Dkk1 expression in bone marrow mesenchymal stem cells (BMSCs) from myeloma patients, but only BMPR1a-FC reduced sclerostin levels in the bone marrow plasma of myeloma-bearing mice, which may explain the stronger anabolic effect of BMPR1a-FC." (PMID 31586071, 2019). "In the bone metastasis of multiple myeloma, MSC-derived factors induced the secretion of Dkk1 from myeloma cells that prevented MSC differentiation to osteoblasts." (PMID 29642534, 2018). "Following engraftment of primary multiple myeloma cells from patients with clinical disease into SCID-rab, anti-DKK1 therapy significantly increased bone mineral density, increased osteoblast number and reduced osteoclast TRAP staining." (PMID 29056680, 2017). "In xenograft models of cancers that include multiple myeloma (MM), osteosarcoma, HCC, lung, and prostate cancers, neutralization or inhibition of DKK1 has been successful in inhibiting tumour growth in some cases or tumours burden in others." (PMID 27367730, 2016). "Leading on from previous findings in multiple myeloma, this study aimed to investigate p38 MAPK as a regulator of DKK-1 in prostate cancer." (PMID 26913608, 2016). "Various soluble factors have been identified in the signaling crosstalk between myeloma and stromal cells including IGF-1, IL6, DKK-1, RANKL and activin A." (PMID 25887188, 2015). "We examined the expression of DKK-1 protein in 6 HMCLs, and 5 freshly purified primary CD138+ myeloma cells and 4 SCs from patients with MM by western blotting." (PMID 20846389, 2010). "Similarly, the co-administration of DKK-1 antibodies and a novel anti-LRP6 antibody also led to superior skeletal outcomes in mouse models of multiple myeloma." (PMID 37174109, 2023). "HFD was found to have no significant impact on DKK1 and total adiponectin concentrations compared to ob/ob mice, suggesting that these factors are not responsible for the myeloma-permissive environment generated by HFD." (PMID 36909335, 2023).